XDH (xanthine dehydrogenase)
Diseases named in the same sentence as XDH in open-access papers (continued):
Sharing a sentence is not in itself a finding about the gene and the disease.
xanthinuria type I (18 papers, 2012 to 2025). "Type I xanthinuria (MIM 278300) is caused by variants in the XDH gene and results in isolated XDH deficiency." (PMID 34356852, 2021). "We report here a case of xanthinuria type I due to the homozygous mutation NM_000379.3(XDH):c2545-1G>C." (PMID 37360896, 2021). "Here we present two Israeli Arab families affected by type I xanthinuria in whom a c.2164A>T (Lys722Ter) variant in the XDH gene, previously reported in a Turkish family of Turkmen origin, was identified." (PMID 32071838, 2020). "Human mutations in xanthine dehydrogenase activity result in the disorder xanthinuria type I. An equivalent disease also occurs in dogs, most notably the Cavalier King Charles spaniel breed." (PMID 25970330, 2015). "Mutations in XDH in man give rise to classical xanthinuria type I, a rare genetic disorder characterised by elevated serum and urinary concentration of xanthine and renal xanthine calculi, in association with undetectable levels of uric acid." (PMID 23024809, 2012). "Homozygous or compound heterozygous pathogenic XDH variants cause type I xanthinuria (XAN1)." (PMID 38397443, 2024). "We report below a new mutation of XDH/XO associated with a case of xanthinuria type I." (PMID 37360896, 2021). "In the case of the type I xanthinuria-causing variant that led to a Cys-to-Phe substitution at position 150, the Arabidopsis thaliana XDH isoform 1 (AtXDH1) was used as a model to study the effect of a substitution of Cys150 in human XDH." (PMID 34356852, 2021). "Variants in the XDH or HMCS gene underlie classical xanthinuria type I and type II, respectively." (PMID 32071838, 2020). "Furthermore, patient with type I xanthinuria presents very low serum uric acid because of deficiency in xanthine dehydrogenase, which catalyzes the oxidation of hypoxanthine to xanthine and also of xanthine to uric acid." (PMID 24628802, 2014). "Type I xanthinuria is associated with XDH/XOR deficiency, whereas type II xanthinuria involves XDH/XOR and aldehyde oxidase (a molybdoflavo enzyme similar to XDH/XOR)." (PMID 35327453, 2022). "Type I xanthinuria was suspected in the first index case, IV-15, due to homozygosity for markers in the XDH gene and was confirmed by the allopurinol loading test in the second index case (V-1) (not shown)." (PMID 34356852, 2021). "Because allopurinol is converted to oxypurinol by XDH/XOR and aldehyde oxidase, allopurinol administration results in the detection of oxypurinol in the urine and serum of patients with xanthinuria type I, but not in those with type II." (PMID 35327453, 2022). "Type I xanthinuria was suggested by homozygosity mapping with markers in the XDH gene, but DNA was not available for further analysis due to the premature death of the index case." (PMID 34356852, 2021). "By contrast, in cases with xanthinuria type I, oxypurinol can be detected as there is still activity for AOX, although there is not for XDH/XO." (PMID 37360896, 2021).
kidney damage (17 papers, 2017 to 2025). "Thus, the differences in XDH expression levels observed in our study could modulate the severity of adenine-induced kidney damage and an increased XDH expression level could plausibly be the cause of exacerbated adenine-induced kidney damage in GF mice." (PMID 32859011, 2020). "Xanthine crystals and nephropathy have been described in rats treated with XDH inhibitors Mice lacking XDH were described in 2009 by Ohtsubo T and co-workers." (PMID 28282408, 2017). "The present study demonstrated that the GF mice displayed increased expression of purine metabolizing enzymes, including XDH, which could promote the conversion of the administered adenine into the nephrotoxic 2,8-DHA, and result in exacerbated adenine-induced kidney damage." (PMID 32859011, 2020).
kidney stones (14 papers, 2004 to 2025). "Here we establish a Drosophila melanogaster model for ectopic calcification by inhibiting xanthine dehydrogenase whose deficiency leads to kidney stones in humans and dogs." (PMID 25970330, 2015). "Xanthine dehydrogenase is deficient in a subset of patients with nephrolithiasis and some dog species." (PMID 25970330, 2015). "Interestingly, knocking down ZnT35C also significantly reduced kidney stone formation in a fly calcification model generated by inhibiting xanthine dehydrogenase (Xdh), suggesting that zinc homeostasis in tubules is important to this physiologic process." (PMID 28196538, 2017). "However, nephrolithiasis and exercise induced renal failure (EIRF) have been reported in individuals with mutations in either the SLC22A12 (URAT1) or SLC2A9 (GLUT9) but not XDH (XO) genes." (PMID 29904633, 2018).
colorectal cancer (13 papers, 2010 to 2025). A primary or metastatic malignant neoplasm that affects the colon or rectum. "Dysregulation of purine metabolism and decreased XDH activity is also associated with the progression of other cancers such as glioblastoma, lung, breast, ovarian, and colorectal cancers." (PMID 39337628, 2024). "In addition, the expression level of XDH has been reported to be available in diagnosing colorectal cancer stages." (PMID 36589748, 2022). "FABP6, hypermethylated SFRP1, XDH, PLAU, ADH1C, HSD17B2, and SPP1 have been identified more as a colorectal cancer biomarker than as a therapeutic target at present." (PMID 34381520, 2021). "We therefore here examined the function of our XO and XDH knock-in mice in the syngenic subcutaneously transplanted colorectal cancer model CMT93." (PMID 31659168, 2019).
hepatocellular carcinoma (13 papers, 2008 to 2025). A malignant tumor that arises from hepatocytes. "However, the prognostic value of XDH in predicting tumor-infiltrating lymphocyte abundance, the immune response, and survival in different cancers, including hepatocellular carcinoma (HCC), is still unclear." (PMID 34496841, 2021). "Researchers have known for decades that XDH activity is decreased in some cancers, including hepatocellular carcinoma (HCC)." (PMID 28945217, 2017). "The expression of XDH inversely correlates with the expression of cancer stem cell–related genes, such as CD44 or CD133, and their downregulation promotes TGFβ signaling in hepatocellular carcinoma." (PMID 37239828, 2023).
Hypercholesterolemia (13 papers, 2009 to 2025). An increased concentration of cholesterol in the blood. "Hypercholesterolemia is often associated with local hypoxia of the blood vessel walls, favoring the conversion of endothelial xanthine dehydrogenase to XO form." (PMID 29590254, 2018). "The pro-oxidant enzymes NOX and XDH/XO were previously shown to contribute to vascular damage during hypercholesterolemia in ApoE−/− mice." (PMID 37873768, 2023).
colon carcinoma (11 papers, 2006 to 2023). "By regression analysis, 6 immune-related DEGs (AEN, F2RL1, NR3C2, PPARGC1A, LGALS4, and XDH) were identified as potential prognostic factors, of which AEN, LGALS4, and XDH were used to construct a risk score model, which can effectively predict overall survival (OS) in colon cancer patients." (PMID 36589748, 2022). "Significant linkage with colon tumor development was observed at this same chromosomal location; in Chromosome 17, the region near 74 Mb harbors the Alk gene (anaplastic lymphoma kinase) that has been targeted for the therapy of some types of lung cancer and the Xdh (xanthine dehydrogenase) gene." (PMID 34966170, 2022). "As the respective roles of XDH and XO and the cells expressing them are not clear in susceptibility to tumor growth, we tested our mice expressing the XO and XDH forms in an in vivo model of subcutaneously transferred CMT93 colon carcinoma cells (expressing WT XOR)." (PMID 31659168, 2019).
liver disease (11 papers, 2015 to 2026). "However, the lack of liver disease-associated SNPs prevented the evaluation of XDH in our MR analysis framework." (PMID 40282409, 2025).
type II xanthinuria (11 papers, 2012 to 2025). "Classical xanthinuria is a rare autosomal recessive metabolic disorder caused by variants in the XDH (type I) or MOCOS (type II) genes." (PMID 34356852, 2021). "Hereditary xanthinuria (HX) is a rare disorder of purine catabolism caused by an inherited xanthine dehydrogenase/oxidase (XDH/XO, EC: 1.17.1.4/1.17.3.2) deficiency, first described in 1954 by Dent and Philpot." (PMID 37360896, 2021). "Hereditary xanthinuria is caused by a deficiency of xanthine dehydrogenase/oxidase (XDH/OX), leading to a reduced degradation of hypoxanthine and xanthine to uric acid, and the accumulation of these two uric acid precursors." (PMID 30157195, 2018). "A linkage analysis with markers within and around the XDH gene showed that the affected individuals were heterozygous for the tested markers, suggesting type II xanthinuria." (PMID 34356852, 2021). "In type II xanthinuria, (MIM 603592) variants in the Molybdenum Cofactor Sulfurase gene (MOCOS, alias HMCS) cause combined XDH and Aldehyde Oxidase (AO; EC 1.17.3.2) deficiency." (PMID 34356852, 2021). "Notably, although the serum and urine levels of xanthine and hypoxanthine as well as the activity of XDH, AOX1, and MOCOS are important diagnostic criteria for Xanthinuria type II, these tests cannot be performed in most hospital laboratories." (PMID 41164817, 2025). "Additionally, mutations in the molybdenum cofactor sulfurase gene (MOCOS, EC: 2.8), mapped to chromosome 18q12.2, raise xanthinuria type II (OMIM 603592), developing both XDH/XO and aldehyde oxidase (AOX) deficiency." (PMID 37360896, 2021).
liver cancer (9 papers, 2017 to 2025). An epithelial or non-epithelial malignant neoplasm that arises from the liver. "HCC cancer stem cells demonstrate xanthine dehydrogenase/oxidase deficiency, with this enzyme loss potentiating the expansion of liver cancer stem cells." (PMID 40311679, 2025). "Low XDH levels are associated with poor prognosis in liver cancer and are believed to contribute to HCC progression." (PMID 39337628, 2024). "Therefore, it is rational to consider liver cancers as a representative human cancer with weak XDH expression." (PMID 34496841, 2021). "In this study, we showed that decreased XDH expression or activity could promote TGFβ-signaling pathway-dependent liver cancer cell migration, invasion and metastases to the lungs." (PMID 28945217, 2017).
asthma (8 papers, 2015 to 2024). "Furthermore, interrogating how other cytokine combinations that are frequently associated with the asthma phenotype (e.g. IL-13, IL-4, TSLP) may reveal novel mechanisms for regulating XDH expression and uric acid production." (PMID 28863172, 2017).
lung adenocarcinoma (7 papers, 2019 to 2023). A carcinoma that arises from the lung and is characterized by the presence of malignant glandular epithelial cells. "XDH, which encodes for xanthine dehydrogenase, has been reported to be highly expressed in a lung adenocarcinoma (LUAD) subtype associated with poor survival." (PMID 32899191, 2020). "The altered expression and activity of XDH are associated with the development and prognosis of multiple types of cancer, while its role in lung adenocarcinoma (LUAD) remains unknown." (PMID 36778128, 2023). "Other researchers have reported that high tumoral XDH expression is an independent predictor of poor prognosis in patients with lung adenocarcinoma." (PMID 35664305, 2022). "In this study, we continue to focus on the germline mutation of genes in lung adenocarcinoma and we have identified seven different variants (SMG5, RAB3GAF2, EI24, XDH, PTPRA, ATR, GSTZ1) in three sibling patients suffering from lung cancer." (PMID 35712480, 2022). "We analyzed lung adenocarcinoma patient data from The Cancer Genome Atlas and identified a subset of patients in which xanthine dehydrogenase (XDH) expression correlated with decreased survival." (PMID 31116490, 2019).
lung carcinoma (7 papers, 2021 to 2025). "However, high XDH mRNA expression was associated with worse OS in patients with gastric cancer and lung cancer." (PMID 34496841, 2021). "In contrast, increased levels of XDH are often observed in cancers originating from tissues expressing low level of XDH including prostate cancer, brain tumor and lung cancer, due to elevated demand for purine metabolism and the activation of the inflammatory response." (PMID 36778128, 2023).
prostate carcinoma (7 papers, 2006 to 2025). A carcinoma that arises from epithelial cells of the prostate gland. "Oxidative stress caused by XDH promotes prostate cancer cell-specific apoptosis." (PMID 35693733, 2022). "Furthermore, both XDH (downregulated in liver tumors) and AVPR1A (upregulated in prostate cancer) have been implicated in the activity of cancer-related stem cells." (PMID 34206369, 2021).
renal fibrosis (7 papers, 2012 to 2025). A final common manifestation of a wide variety of chronic kidney diseases characterized by glomerulosclerosis and tubulointerstitial fibrosis. "This mouse model could help to increase our understanding of the molecular mechanisms associated with renal fibrosis and the specific roles of XDH and uric acid." (PMID 23024809, 2012).
anemia (6 papers, 2018 to 2025). A reduction in the number of red blood cells, the amount of hemoglobin, and/or the volume of packed red blood cells. "Neither XO-type- nor XDH-type KI mutants altered aging-like phenotypes, such as anemia, fatty liver, muscle atrophy, and bone loss, in Sod1−/− mice." (PMID 33805516, 2021).
Cachexia (6 papers, 2012 to 2021). Severe weight loss, wasting of muscle, loss of appetite, and general debility related to a chronic disease. "Although XO is not usually present at high levels within skeletal muscle, the hyperactivation of XO during cachexia could be explained by an increase in the cleavage of XDH to XO." (PMID 27642498, 2016). "The abundance of pro-inflammatory factors present in cachexia may lead to an increase in the cleavage of XDH to the XO form, explaining higher circulating levels of XO." (PMID 23029301, 2012).
glioblastoma (6 papers, 2011 to 2024). The most malignant astrocytic tumor (WHO grade IV). "For example, glioblastoma were found to express extremely low levels of the mRNA encoding uricogenesis enzymes (in particular XDH)." (PMID 30104401, 2018).
Hepatic fibrosis (6 papers, 2011 to 2023). The presence of excessive fibrous connective tissue in the liver. "Although STAT1 and HSP90AA1 have no direct targets, SCST indirectly affects PPARG, STAT1 and HSP90AA1 to exert anti-fibrosis effects through XDH, which is also closely related to liver fibrosis." (PMID 33510287, 2021).
malaria (6 papers, 2012 to 2023). Malaria is a serious and sometimes fatal disease caused by a parasite that commonly infects a certain type of mosquito which feeds on humans. "The enzyme precursor of XO, xanthine dehydrogenase, is upregulated by activation of type I IFN receptor very early upon Plasmodium infection in mice, suggesting that early sensing of malaria results in increased oxidative stress." (PMID 31265218, 2019).
bladder cancer (5 papers, 2011 to 2023). "XDH activity significantly increased in multiple cancer types including bladder cancer 54, small cell and non-small cell lung cancer." (PMID 36778128, 2023).
fibrosis (5 papers, 2015 to 2025). the formation of excess fibrous connective tissue in an organ or tissue in a reparative or reactive process. "However, when adenine is administered in excess, APRT activity is saturated, and adenine is oxidized by xanthine dehydrogenase to 2,8-dihydroxyadenine, which forms precipitates and crystals in the renal tubules, resulting in tubular fibrosis, inflammation, and obstruction." (PMID 40723373, 2025).
influenza (5 papers, 2018 to 2024). An acute viral infection of the respiratory tract, occurring in isolated cases, in epidemics, or in pandemics; it is caused by serologically different strains of viruses (influenzaviruses) designated A, B, and C, has a 3-day incubation period, and usually lasts for 3 to 10 days. "For example, in mice infected with influenza, the ratio of XO to XDH activity in samples of alveolar lavage fluid increased from ~0.15 to 1.06." (PMID 37190079, 2023).
leukemia (5 papers, 2019 to 2023). A malignant (clonal) hematologic disorder, involving hematopoietic stem cells and characterized by the presence of primitive or atypical myeloid or lymphoid cells in the bone marrow and the blood. "The expression of XDH decreased in some cancer types such as prostate, colon, breast, liver, bladder, and leukemia." (PMID 35664305, 2022).
dilated cardiomyopathy (4 papers, 2011 to 2023). Cardiomyopathy which is characterized by dilation and contractile dysfunction of the left and right ventricles. "Xanthine oxidase and xanthine dehydrogenase were highly expressed in the myocardium of patients with dilated cardiomyopathy." (PMID 36832278, 2023). "In addition, protein expressions of xanthine dehydrogenase (XDH) and xanthine oxidase (XO) are increased in the myocardium of patients with dilated cardiomyopathy." (PMID 35077456, 2022).
glioma (4 papers, 2018 to 2022). A benign or malignant brain and spinal cord tumor that arises from glial cells (astrocytes, oligodendrocytes, ependymal cells). "Indeed, analysis of the GEPIA database revealed that low XDH expression was correlated with a worse prognosis in cancer types such as CHOL, lower grade glioma (LGG), LUAD, and thyroid carcinoma (THCA)." (PMID 34496841, 2021).
kidney injuries (4 papers, 2020 to 2022). "When examining the effects of certain interventions such as drugs and genetic modifications on adenine-induced kidney injuries, we need to consider the possible effects on the purine metabolism including the expression and activity of XDH." (PMID 32859011, 2020).
pancreatic cancer (4 papers, 2006 to 2022). "In several malignancies, including pancreatic cancer, XDH, a rate-limiting enzyme that catalyzes the last stage of purine metabolism, was a reliable predictor for poor prognosis in many cancers including pancreatic cancer." (PMID 36685915, 2022). "In HCT-BR cells, XDH exerts purine oxidation and electron acceptor functions and is highly expressed in uterine corpus endometrial carcinoma and lung and pancreatic cancers." (PMID 35909471, 2022). "Furthermore, an overview of up-regulated overlapping genes in all sorts of tumors showed that up-regulated overlapping genes, except XDH, were observably overexpressed in pancreatic cancer." (PMID 32537471, 2020).
APRT deficiency (3 papers, 2020 to 2025). "Symptoms of APRT deficiency can be treated by allopurinol or febuxostat, which are inhibitors of XDH, preventing excessive formation of toxic 2,8-DHA." (PMID 32260098, 2020).
colon adenocarcinoma (3 papers, 2016 to 2022). "Furthermore, XDH is expressed at lower levels in colon adenocarcinoma tissue than in healthy tissue." (PMID 35909471, 2022).
dementia (3 papers, 2019 to 2023). Loss of intellectual abilities interfering with an individual's social and occupational functions. "XO/XDH inhibitors have been reported to suppress the onset of dementia." (PMID 36380272, 2022). "It is also known that inhibitors of XO/XDH prevent the onset of heart disorders and dementia, similar to aging." (PMID 36380272, 2022).
Infertility (3 papers, 2013 to 2025). "Additionally, knocking-down the enzyme considered to be the key bottleneck in purine degradation, xanthine dehydrogenase, resulted in reduced growth, early senescence and infertility." (PMID 23957885, 2013).
serous ovarian cancer (3 papers, 2016 to 2022). "For instance, low expression of XDH predicted a poor prognosis in patients with breast and serous ovarian cancer." (PMID 36589748, 2022).
uterine corpus endometrial carcinoma (3 papers, 2021 to 2022). A endometrial carcinoma (disease) that involves the body of uterus. "Additionally, in TCGA, XDH mRNA expression was lower in kidney chromophobe (KICH) and cholangiocarcinoma (CHOL) tumor tissues and higher in esophageal carcinoma (ESCA) and uterine corpus endometrial carcinoma (UCEC) than in adjacent normal tissues." (PMID 34496841, 2021).